AMPD2 (adenosine monophosphate deaminase 2)
Description:
AMP deaminase plays a critical role in energy metabolism. Catalyzes the deamination of AMP to IMP and plays an important role in the purine nucleotide cycle.
Synonyms: SPG63; AMPD; PCH9
Tractability: Small molecule: a structure with a bound ligand is known; it belongs to a druggable protein family. PROTAC: ubiquitination databases record sites on it; its protein half-life has been measured; a small molecule that binds it is known.
Target class: Enzyme; Hydrolase
Gene: Protein-coding gene on chromosome 1 (109,616,104 to 109,632,055, forward strand). Ensembl gene ENSG00000116337.
Subcellular location (Human Protein Atlas): Cytosol
Pathways (Reactome):
Metabolism: Purine salvage
Gene Ontology:
Molecular function: AMP deaminase activity; protein binding; deaminase activity
Biological process: cyclic purine nucleotide metabolic process; energy homeostasis; GMP salvage; IMP biosynthetic process; AMP metabolic process; ATP metabolic process; GTP metabolic process; IMP salvage; purine ribonucleoside monophosphate biosynthetic process; purine ribonucleotide salvage
Cellular component: cytosol
Genetic constraint (gnomAD): Loss-of-function variants: 52 observed, 92.98 expected, observed/expected ratio (o/e) 0.56, 90% interval 0.45 to 0.7. The upper end of that interval is the gene's LOEUF score, 0.7, which puts it in group 2 of 6, group 1 being the genes least tolerant of losing a copy. Missense variants: 822 observed, 1,161.7 expected, observed/expected ratio (o/e) 0.71, 90% interval 0.67 to 0.75. Synonymous variants: 455 observed, 477.81 expected, observed/expected ratio (o/e) 0.95, 90% interval 0.88 to 1.03.
Homologues: Orthologues: chimpanzee AMPD2 (99% identical), macaque AMPD2 (99% identical), guinea pig AMPD2 (98% identical), dog AMPD2 (98% identical), rat Ampd2 (96% identical), pig AMPD2 (95% identical), rabbit AMPD2 (95% identical), mouse Ampd2 (94% identical), tropical clawed frog ampd2 (80% identical), zebrafish ampd2b (73% identical), zebrafish ampd2a (72% identical), Drosophila melanogaster AMPdeam (52% identical), and 1 more. Paralogues in human: AMPD3 (48% identical), AMPD1 (45% identical).
Diseases named in the same sentence as AMPD2 in open-access papers:
AMPD2 is named in the same sentence as 37 diseases in open-access papers, as found by Europe PMC text mining. Sharing a sentence is not in itself a finding about the gene and the disease. The quoted sentences say what the papers report.
pontocerebellar hypoplasia type 9 (3 papers, 2024 to 2025). Any non-syndromic pontocerebellar hypoplasia in which the cause of the disease is a mutation in the AMPD2 gene. "Inactivating mutations in AMPD2 cause Pontocerebellar Hypoplasia type 9 (PCH9)." (PMID 39075237, 2024). "The homozygous variant of the AMPD2 gene on chromosome 1p13 causes pontocerebellar hypoplasia type 9 (PCH9) and spastic paraplegia-63 (SPG63)." (PMID 40217360, 2025). "Pontocerebellar hypoplasia type 9 (PCH9) is a rare, autosomal, recessive, neurodevelopmental disorder caused by a mutation in the AMPD2 gene." (PMID 38957830, 2024).
COVID-19 (2 papers, 2022 to 2025). A disease caused by infection with severe acute respiratory syndrome coronavirus 2. "We validated this prediction using bulk RNA-seq and clinical scRNA-seq data, confirming that AMPD2 expression is downregulated in severe COVID-19 but restored upon A3B knockdown." (PMID 41012606, 2025). "The clinical data further corroborate the inverse relationship between A3B and AMPD2 expression in severe COVID-19." (PMID 41012606, 2025). "Rather, it appears to suppress AMPD2 expression, possibly leading to the elevated purine nucleotide synthesis and altered anti-inflammatory purinergic signaling, contributing to cytokine release syndrome and worsening disease severity in COVID-19 patients." (PMID 41012606, 2025). "To further investigate A3B’s role in severe COVID-19, we employed Geneformer, a transformer-based machine learning model, which predicted that A3B knockout would perturb AMPD2 (adenosine monophosphate deaminase 2), a key enzyme in purine metabolism and immune regulation." (PMID 41012606, 2025). "To explore a potential relationship between A3B and AMPD2, we examined scRNA sequencing data from BALF of severe and mild COVID-19 patients." (PMID 41012606, 2025). "Neutrophil transcripts which are robustly expressed in the uninfected state, including anti-proliferation and pro-apoptotic genes (LST1, G0S2, CPPED1, BTG2, PMAIP1) and anti-inflammatory genes (AMPD2, SEC14L1, ZFP36), are significantly downregulated in COVID-19 patients." (PMID 36466858, 2022).
dyslipidemia (2 papers, 2014 to 2025). "While previous studies on the PNC have largely been confined to skeletal muscle, and renal research has primarily focused on its role in ammoniagenesis, hepatic AMPD2 has been implicated in metabolic syndromes induced by monosodium glutamate or high-fat diets." (PMID 41471373, 2025). "If the hepatic deficiency of Ampd2 is the primary cause of the dyslipidemia, the defect in purine catabolism as here could provide a pathogenic mechanism." (PMID 25361754, 2014). "Collectively, these data suggest that dyslipidemia is a direct consequence of Ampd2 deficiency, and not a consequence of NS." (PMID 25361754, 2014). "Moreover, no changes were observed in the expression of glomerular AMPD2 in rats with fructose-induced metabolic syndrome, with or without morin intervention, as shown by immunofluorescence assay." (PMID 41471373, 2025).
fatty liver (2 papers, 2012 to 2015). "AMPD2 activity is high during the summer in association with the development of hepatic steatosis and low AMPK activity." (PMID 25856396, 2015). "In this manuscript, we characterize the activity of another AMP dependent protein, AMPD2 (AMP deaminase 2) in an in vitro and in vivo model of hepatic steatosis, fructose-induced fatty liver." (PMID 23152807, 2012). "In this study, we investigated the relationship of two AMP-dependent enzymes, AMPD2 and AMPK, in the development of fatty liver induced by fructose." (PMID 23152807, 2012). "While it is well-known that AMPK stimulates fat oxidation and inhibits lipogenesis, no studies to date have investigated the interaction of AMPD2 and AMPK in fructose-induced fatty liver." (PMID 23152807, 2012).
Hypercholesterolemia (2 papers, 2014 to 2024). An increased concentration of cholesterol in the blood. "In the mouse, mutations of AMPD2 are associated with hypercholesterolemia, resembling the human disorder." (PMID 38397227, 2024). "In conclusion, we have identified a novel mouse model of transient hypercholesterolemia with concurrent NS associated with defective Ampd2 function." (PMID 25361754, 2014). "In the present study, we identified a mutation in the Ampd2 gene that leads to NS and hypercholesterolemia." (PMID 25361754, 2014). "Ascertaining whether the two phenotypes are interrelated and the molecular mechanism of Ampd2 loss and hypercholesterolemia will require further investigation." (PMID 25361754, 2014). "Ampd2 homozygous mutant mice exhibit a labile hypercholesterolemia phenotype, peaking around 9 weeks of age (251 mg/dL vs. wildtype control at 138 mg/dL), and was evidenced by marked increases in HDL, VLDL and LDL." (PMID 25361754, 2014). "We further characterize the Ampd2 mutant mice as having a transient hypercholesterolemia phenotype that also present with transient nephrotic syndrome (NS)." (PMID 25361754, 2014).
microcephaly (2 papers, 2024 to 2025). A congenital or acquired developmental disorder in which the circumference of the head is smaller than normal for the person's age and sex. "All of the genes associated with microcephaly or cerebellar hypoplasia, except for AMPD2/SPG63, were highly expressed during the embryonic period." (PMID 39932116, 2025). "Biallelic variants in adenosine monophosphate deaminase 2 (AMPD2/SPG63) caused pontocerebellar hypoplasia with unique combination of postnatal microcephaly, hypoplastic cerebellum and pons, and hypoplastic or absent corpus callosum." (PMID 39932116, 2025).
viral infection (2 papers, 2024 to 2025). "Specifically, elevated A3B expression occurs in response to viral infection and inflammatory signaling, potentially repressing AMPD2 to further increase AMP accumulation and subsequent cytokine release." (PMID 41012606, 2025).
Alzheimer disease (1 paper, 2020). A progressive, neurodegenerative disease characterized by loss of function and death of nerve cells in several areas of the brain leading to loss of cognitive function such as memory and language. "Theoretically, regulating KHK-C in the brain, or regulating AMPD2, might provide novel ways to prevent and treat Alzheimer’s disease." (PMID 33024433, 2020).
Hypoglycemia (1 paper, 2024). A decreased concentration of glucose in the blood. "In our proposed mechanism, hypoglycemia is the only F1P-dependent and AMPD2-independent condition in HFI and relies on the rapid ingestion of high amounts of fructose." (PMID 38992061, 2024). "While blocking AMPD2 do not impact F1P accumulation and the risk of hypoglycemia, its deletion in hepatocytes markedly improves the metabolic dysregulation induced by fructose and corrects fat and glycogen storage while significantly increasing the voluntary tolerance of these mice to fructose." (PMID 38992061, 2024).
interstitial nephritis (1 paper, 2014). Inflammation of the renal tubules and supporting tissues of the kidney. "Proteinaceous tubular casts and interstitial nephritis were observed in Ampd2m/m mice and not Ampd2+/+ mice." (PMID 25361754, 2014).
Obesity (1 paper, 2015). Accumulation of substantial excess body fat. "And in the groups with diet-induced-obesity (OB), both adenosine monophosphate deaminase 2 (Ampd2) and adenosine deaminase (Adat2) were up-regulated." (PMID 26609465, 2015).
psoriatic arthritis (1 paper, 2019). Joint inflammation associated with psoriasis. "Biologic drugs are increasingly being prescribed for psoriatic arthritis and it is worth mentioning that (with possible exception of tofacitinib for AMPD2) none of the drugs targeting the genes we identify are biologics." (PMID 31031798, 2019).
sarcoma (1 paper, 2020). A usually aggressive malignant neoplasm of the soft tissue or bone. "And AMPD2 was identified as a potential biomarker for predicting the poor prognosis of undifferentiated pleomorphic sarcoma functional genomics identifies." (PMID 32953885, 2020).
Spastic paraplegia (1 paper, 2024). Complete loss of the ability to move the lower limbs accompanied by spasticity of the lower limbs. "Expanding the spectrum of phenotypes associated with AMPD2, Novarino and colleagues identified a homozygous frameshift mutation that occurred in affected members of a consanguineous family affected by spastic paraplegia." (PMID 38397227, 2024).
tumor (4 papers, 2017 to 2023). "Together with the finding that AMPD2 may promote tumor growth and proliferation, AMPD2 could be a promising prognostic biomarker for UPS." (PMID 35875106, 2022).
kidney disease (2 papers, 2014 to 2017). "The combined phenotypes have not previously been reported in Ampd2 knockout mice; minimal change kidney disease was observed in these mice, and it was speculated that Ampd2 function was critical for podocyte survival and related to defects in Inosine-5′-monophosphate (IMP)." (PMID 25361754, 2014). "Furthermore, AMPD2, the renal AMP deaminase isoform, would be a key target in the pathogenesis of AKI as its blockade would prevent both the early and late ATP depletion, and therefore it would be more beneficial to accelerate kidney disease post-AKI." (PMID 28194018, 2017).
infection (1 paper, 2025). The state of being infected such as from the introduction of a foreign agent such as serum, vaccine, antigenic substance or organism. "We observed a trend toward elevated A3B expression and reduced AMPD2 expression in severe cases relative to mild infection." (PMID 41012606, 2025).
AMPD2 also shares sentences with these, for which no sentence is quoted: breast carcinoma (1 paper); developmental delay (1); Dystonia (1); Failure to thrive (1); Fanconi syndrome (1); fructose intolerance (1); hepatocellular carcinoma (1); hereditary spastic paraplegia (1); Hypertonia (1); Hypotonia (1); liver disease (1); lymphoma (1); melanoma (1); nephrotic syndrome (1); neurodevelopmental disorder (1); ovarian carcinoma (1); primary optic atrophy (1); retinal degeneration (1); Retinopathy (1); systemic lupus erythematosus (1).